H19 (H19 imprinted maternally expressed transcript)
Diseases named in the same sentence as H19 in open-access papers (continued):
Sharing a sentence is not in itself a finding about the gene and the disease.
Obesity (continued). "The aims of the present study were to characterize the relationship of levels of lncRNA H19 in plasma and different adipose tissue depots with response to bariatric surgery in patients with obesity." (PMID 35629301, 2022). "We earlier reported that obesity was associated with lower methylation at the MEG3, SNRPN, and SGCE/PEG10 DMRs, and increased DNA methylation at MEG3-IG and H19 DMRs." (PMID 33494820, 2021). "In the present study, we concluded that H19-mediated Pink1 regulation is critically involved in obesity-induced mitochondrial suppression and cardiac dysfunction." (PMID 34050133, 2021). "H19 inhibits excessive mitophagy by limiting Pink1 mRNA translation, thus alleviating this cardiac defect that occurs during obesity." (PMID 34050133, 2021). "Among the lncRNAs potentially involved in obesity-induced cardiac function, lncRNA H19 (H19) warrants investigation." (PMID 34050133, 2021). "To investigate the biological roles of H19 in glucose metabolism and its potential contributions to the development of obesity-induced insulin resistance, we used db/db mice as a model for obesity and insulin resistance." (PMID 33115498, 2020). "In one study, it was observed that the lncRNA H19 was related to brown adipocyte differentiation and was decreased in obesity in BAT under an obese state." (PMID 32765426, 2020). "Several cohort studies have found associations between inter-individual genetic variations in the INS/IGF-II/H19 locus and body weight and obesity as well as with abdominal and visceral fat." (PMID 31590432, 2019). "Other studies underlined the relationship between IGF2/H19 IC1 DNA methylation and the development of overweight/obesity." (PMID 30619799, 2018). "Then we validated 7 obesity or lipid metabolism related genes (Hif1a, Spon1, H19, Adrb2, Vldlr, Zfp36, Smad3), and found that compared to CTL group, Vldlr was hypermethylated and low expressed, and Hif1α was demethylated and high expressed in the VDD group." (PMID 29321608, 2018). "We observed maternally expressed, imprinted lncRNA H19 increased upon cold-activation and decreased in obesity in BAT." (PMID 30190464, 2018). "Recently, it has also been shown that polymorphisms in H19 are correlated with CAD and CAD risk factors, such as obesity, high birth weight, and hypertension." (PMID 27317124, 2016). "Other genes involved in obesity (e.g., Cidec, Cd36), diabetes (Igfbp1), inflammation (Cd63), mitochondrial function (Pdk4) and cancer (H19) were also upregulated by the soybean oil diet." (PMID 26200659, 2015). "In the present study, we found the DNA methylation patterns at the DMRs of H19 and Peg3 in spermatozoa of offspring were influenced by pre-existing maternal diabetes and obesity, respectively." (PMID 24721882, 2014). "Our data suggest an increase in DNA methylation at the IGF2 and H19 DMRs among newborns from obese mothers, but a larger study is warranted to further explore the potential effects of maternal obesity or lifestyle on the offspring's epigenome." (PMID 23388414, 2013). "Understanding the role of H19 offers valuable opportunities to develop targeted interventions that may reduce the transgenerational effects of obesity." (PMID 41905454, 2026). "Notably, H19, MEG3, GAS5, miR-26a-1-3p, and miR-376a-3p have been implicated in both asthma and obesity, suggesting their role in linking metabolic dysfunction with airway pathology." (PMID 41156032, 2025). "Another study has indicated that enhancement of function of H19 would have anti-obesity impacts." (PMID 37326896, 2024). "Recently, many studies have suggested that lncRNAs, such as Metastasis Associated Lung Adenocarcinoma Transcript 1 (MALAT1) and Imprinted Maternally Expressed Transcript (H19), might participate in the pathogenesis of metabolic disorders such as obesity." (PMID 37104004, 2023). "Moreover, H19 participates in lipogenesis regulation, adipose tissue metabolism, and insulin sensitivity, and consequently plays a role in obesity pathogenesis." (PMID 37104004, 2023).
Obesity (continued). "One of the factors affecting the differences in the expression of lncRNA H19 in patients with obesity and obesity accompanied by ICM may be a decrease in energy deficit at higher glycemic levels." (PMID 35629301, 2022). "Overall, these data suggested a potential anti-obesity effect of H19." (PMID 36555704, 2022). "In an experimental model of obesity in mice, it was shown that the levels of lncRNA H19 change in the brown adipose tissue during development of obesity, and that increased expression of lncRNA H19 protects animals from the development of high-fat diet-induced obesity." (PMID 35629301, 2022). "ICM affects expression of lncRNA H19 in SAT of patients with obesity." (PMID 35629301, 2022). "In conclusion, ICM affects expression of lncRNA H19 in SAT of patients with obesity." (PMID 35629301, 2022). "It proves that obesity factors affect the expression of H19 in exosomes." (PMID 33471953, 2021). "We next investigated whether restoring H19 expression could alleviate cardiac dysfunction in the setting of obesity." (PMID 34050133, 2021). "We also found that H19 and Hoxa10 have the same expression trend, so we next consider whether the competing endogenous RNA (ceRNA) mechanism is involved in the process of obesity affecting fracture healing." (PMID 33471953, 2021). "Long non-coding RNA H19 (H19) is crucial for metabolic regulation, but its roles in cardiac disorders, mitochondrial respiratory function, and mitophagy during obesity are largely unknown." (PMID 34050133, 2021). "Therefore, in the current study, we performed in vivo and in vitro analyses to investigate the roles of H19, mitophagy, and mitochondrial respiratory function in the heart during obesity." (PMID 34050133, 2021). "In hepatic, adipose, and β-cells, H19 counteracts obesity and relieves insulin resistance." (PMID 34050133, 2021). "Interestingly, H19 has been described to play a role in obesity-induced cancer and to promote epithelial-mesenchymal transition of CRC, with a reported poor prognosis for cancer patients exhibiting H19 induction." (PMID 32714872, 2020). "A number of esophageal cancer-related lncRNAs were dysregulated in obesity such as ANRIL, H19, and HOTAIR, suggesting that obesity-associated lncRNAs may promote development of cancer." (PMID 32133283, 2020). "In addition, the lncRNA with the highest degree is H19, which is related to obesity, type 2 diabetes mellitus, and hypo-HDL cholesterolemia, and is reported to be involved in the pathogenesis of metabolic syndrome." (PMID 31637139, 2019). "The connection of the H19 locus to growth disorders may suggest a possible involvement of the H19 locus in being overweight and obesity." (PMID 23429271, 2013). "We explored the potential effect of parental obesity on IGF2/H19 DMR methylation in newborns." (PMID 23388414, 2013). "Previous work showed that the skeletal muscle-enriched lncRNA H19 enhances muscle insulin sensitivity by activating AMPK, and the administration of H19 RNA increases the basal metabolic rate and protects against high-fat diet (HFD)- or leptin deficiency-induced obesity." (PMID 36604148, 2022). "However, the roles of H19 in mitochondrial mitophagy and function, which is critically involved in obesity-induced cardiac damage, are unknown." (PMID 34050133, 2021). "In addition, H19 transgenic mice were shown to be protected from diet-induced obesity." (PMID 32765426, 2020). "In addition, hypomethylation of IGF2 DMR was also associated with elevated plasma IGF2 protein concentrations and higher birth weight in infant born to obesity women while patterns of association were not apparent at the H19 DMR." (PMID 25269528, 2014). "In ob/ob mouse hearts, the long non-coding RNA H19 has been shown to inhibit excessive PINK1/Parkin-dependent mitophagy by restricting the translation of Pink1 mRNA, thereby ameliorating obesity-related cardiomyopathy." (PMID 40004130, 2025).
Obesity (continued). "In this work, lncRNA H19 was detected in SAT and VAT, as well as in the plasma of the patients with obesity." (PMID 35629301, 2022). "Our study suggested the functional importance of the H19 GOF mutant in enhancing muscle performance and anti-obesity effects." (PMID 34454586, 2021). "Here, we summarize the emerging findings for three well-known oncogenic lncRNAs (namely, ANRIL, H19, and HOTAIR) and discuss their potential roles in obesity-induced cancers." (PMID 30154386, 2018). "The emerging findings for three well-known oncogenic lncRNAs (namely, antisense non-coding RNA in the INK4 locus (ANRIL), H19, and HOX transcript antisense RNA (HOTAIR)) and their potential roles in obesity-induced cancers are discussed." (PMID 30154386, 2018). "For example, obesity has been shown to alter germline DNA methylation profiles in mice, affect fetal and placental gene expression, and modulate offspring hepatic gluconeogenesis via IGF2/H19 gene methylation changes." (PMID 40960588, 2025). "The results of the relationship between H19DMR methylation with obesity and the expression of the H19 and IGF2 genes indicate that fat intake during the first trimester of pregnancy significantly impacts DNA methylation in the IGF2 and H19 genes in newborns." (PMID 39399112, 2024). "Patients with obesity without ICM have higher levels of lncRNA H19 in VAT compared to SAT, and higher levels of lncRNA H19 in SAT compared to SAT of control individuals." (PMID 35629301, 2022). "The preoperative level of lncRNA H19 in VAT correlates with %EWL one year after surgery; therefore, this parameter can be used as a biomarker to predict patient response to bariatric treatment of obesity." (PMID 35629301, 2022). "One year after the intervention, levels of lncRNA H19 decreased in SAT of patients with obesity without ICM." (PMID 35629301, 2022). "Second, we did not detect these effects of H19 in the late stage of obesity, wherein mitophagy is reduced rather than enhanced." (PMID 34050133, 2021). "Taken together, our findings suggested that H19-GOF plays important roles in modulating the metabolic balance of skeletal muscles, leading to muscular hypotrophy and resistance to HFD or leptin resistance-induced obesity." (PMID 34454586, 2021). "We reasoned that RNA oligonucleotides representing the H19-GOF mutant might improve the animals’ skeletal muscle differentiation, muscle strength, performance, and obesity resistance in vivo." (PMID 34454586, 2021). "In this regard, we selected four maternally imprinted genes (MEST/PEG1, SNRPN/PEG4, NNAT/PEG5, and SGCE/PEG10), three paternally imprinted loci (H19-IG DMR, IGF2 DMR0, and MEG3-IG DMR) and one obesity related gene HIF3A to check the correlation of male BMI with sperm DNA methylation." (PMID 31246962, 2019). "This study represents the first exploration of the effects of the HC and LC exercise protocols, with or without the consumption of BBR, on CRP, IL‐1β, NLRP3, and H19 in middle‐aged men with overweight or obesity and prediabetes, which can be considered an advantage." (PMID 39107107, 2024). "In addition, whether H19 is involved in the regulation of obesity fracture healing process has not been reported yet." (PMID 33471953, 2021). "The negative correlation between levels of lncRNA H19 in VAT and initial BMI highlights the role of VAT in the development of obesity and supports the hypothesis of the participation of lncRNA H19 in the molecular pathways of obesity development." (PMID 35629301, 2022).
liver fibrosis (50 papers, 2014 to 2025). "The lncRNA H19 exhibits associations with metabolic risk factors, liver function, and liver fibrosis, and can serve as a potential diagnostic biomarker for MAFLD." (PMID 40101079, 2025). "The DNA methyltransferase 1 (DNMT1)-mediated epigenetic silencing of lncRNA H19 is associated with the activation of hepatic stellate cells, which is involved in liver fibrosis." (PMID 38540698, 2024). "Li et al42 reported that liver H19 levels were strongly associated with macrophage activation and liver fibrosis in BDL and Mdr2−/− animal models and PBC or PSC patients." (PMID 37326156, 2023). "H19 deficiency had an obvious protective effect on hepatic fibrosis in Mdr2−/− and bile duct ligation (BDL) mice." (PMID 37326156, 2023). "Our prior studies identified that lncRNA H19 rapidly and highly expressed in the liver of patients with liver fibrosis and was closely associated with the progression of liver fibrosis." (PMID 36276639, 2022). "We and others have previously reported that aberrant expression of lncRNA H19 is closely associated with hepatic inflammation and liver fibrosis in various liver diseases, including NASH." (PMID 36224648, 2022). "Overexpression of H19 in livers using adeno-associated virus serotype 9 (AAV9) counteracts the effects of macrophage depletion on liver fibrosis and cholangiocyte proliferation." (PMID 34168124, 2021). "The pathogenic role of lncRNA H19 (H19) has been elucidated in a number of inflammatory and organ fibrosis diseases, such as osteoarthritis, ulcerative colitis, liver fibrosis, renal fibrosis, and pulmonary fibrosis." (PMID 30287731, 2018). "The aberrant expression of H19 is associated with liver fibrosis in HCC patients." (PMID 36224648, 2022). "Disruption of lncRNA H19 was associated with attenuation of hepatic fibrosis." (PMID 32507765, 2020). "Conversely, H19 deficiency protected from liver fibrosis induced by BDL and in Mdr2-/- mice." (PMID 33086678, 2020). "A study has shown that H19 exacerbates liver fibrosis by interacting with miR-148a to induce overexpression of USP4, leading to activation of HSCs by inhibiting degradation of Smad4 or TGF-βRI and enhancing TGF-β signaling." (PMID 39195573, 2024). "H19, as a ceRNA, has been demonstrated to play a role in liver fibrosis in cholestatic liver injury by modulating specific targets." (PMID 39195573, 2024). "The study revealed that overexpression of H19 RNA in the liver increased liver fibrosis in BDL mice, accompanied by elevated serum markers of liver damage and altered bile acid levels." (PMID 38511056, 2024). "For instance, H19 promotes the expression of let-7 via suppressing PTBP1 binding to the let-7 precursors in the process of cholestatic hepatic fibrosis." (PMID 37805473, 2023). "We continued to delve into this question about how lncRNA H19 influenced the pathological microenvironment and liver fibrosis via EVs." (PMID 36276639, 2022). "Studies by others have found that metformin suppressed inflammation in diabetic nephropathy by inhibiting H19 expression and that dihydroartemisinin inhibited the development of liver fibrosis." (PMID 36188624, 2022). "Here, we also showed that H19 deficiency reduced the BDL-induced hyperplasia of cholangiocytes and ameliorated liver fibrosis, as indicated by downregulation of the protein expression of CK19, PCNA, α-SMA, and collagen I." (PMID 34168124, 2021).
liver fibrosis (continued). "In contrast, exogenous lncRNA H19 promotes liver fibrosis and enhances the activation and proliferation of HSC." (PMID 34899344, 2021). "Knockdown of H19 or treatment with an H19 inhibitor leads to impaired activation of HSCs and reduces liver fibrosis." (PMID 33671241, 2021). "DNMT1 expression is increased in activated HSCs and rat liver fibrosis tissue, which leads to enhanced methylation of the lncRNA H19 promoter and elevates H19 expression and ERK activation." (PMID 33791228, 2021). "Our previous study indicated that H19 expresses in hepatic macrophages and plays a vital role in regulating bile duct cell proliferation and liver fibrosis in BA patients." (PMID 34168124, 2021). "In conclusion the results highlight the role of H19 in the proliferation, activation and metabolism of lipid droplets in HSCs and reveal its feasibility as a new molecular target to attenuate liver fibrosis." (PMID 34899344, 2021). "H19 not only contributes to bile acid dysregulation via inhibiting small heterodimeric partner expression in hepatocytes but also promotes liver fibrosis by activating hepatic stellate cells." (PMID 34168124, 2021). "In liver fibrosis, numerous lncRNAs such as MALAT1, LFAR1, H19, and NEAT1 was implicated in various inflammatory chemokine pathways including transforming growth factor β (TGF-β), activation of macrophage, and C-X-C motif chemokine ligand 5 (CXCL5)." (PMID 34938356, 2021). "RNA H19 is a competitor of miR-148a, a member of the miR-148/152 family that is downregulated in liver fibrosis." (PMID 33409282, 2020). "On the contrary, a more recent study demonstrated that H19 overexpression in the liver promoted liver fibrosis in the bile duct ligation (BDL) model, Mdr2-/- mice and upon CCl4 treatment in mice." (PMID 33086678, 2020). "The mechanism of action of H19 in liver fibrosis is related to DNA methylation, and the DNA methylation reader protein DNMT1 regulates the lncRNA H19/ERK (extracellular regulated protein kinases) signalling pathway in HSC activation and fibrosis." (PMID 32098245, 2020). "H19 plays an important role in the process of liver fibrosis, with inhibition and promotion mediated by different targets." (PMID 32098245, 2020). "In biliary atresia (BA)-related liver fibrosis, the severity of fibrotic liver injuries in BA patients is correlated with hepatic exosomal H19 levels." (PMID 32098245, 2020). "The others and our recent studies both indicate that hepatic H19 level is correlated with the severity of cholestatic injury and liver fibrosis in mice." (PMID 33138822, 2020). "Our previous study reported that bile acid-induced upregulation of H19 in cholangiocytes contributed to the dysregulation of hepatic bile acids and the progression of liver fibrosis in both Mdr2-/- mice and BDL mice." (PMID 31940841, 2020). "H19 deficiency in DKO mice significantly reduced inflammatory cell infiltration and liver fibrosis when compared with Mdr2-/- mice." (PMID 31940841, 2020). "H19 is upregulated during cholestatic liver injury, and H19−/− mice represent attenuated liver fibrosis during BDL compared to wild-type mice." (PMID 32154257, 2020). "Increased levels of long noncoding RNA H19 (H19) have been observed in many inflammatory and organ fibrosis diseases including ulcerative colitis, osteoarthritis, liver fibrosis, renal fibrosis and pulmonary fibrosis." (PMID 29062612, 2017). "The molecular basis by which H19 regulates the development of liver fibrosis remains to be elucidated using H19 knockout mice in future studies." (PMID 26838806, 2016). "We show that forced expression of Bcl2 in liver disrupts BA homeostasis leading to severe cholestatic liver fibrosis, which is accompanied by the drastic induction of H19." (PMID 26838806, 2016).